LINC00523 (long independently transcribed non-coding RNA 523)
Synonyms: C14orf70
Gene: Long non-coding RNA gene on chromosome 14 (100,657,245 to 100,676,069, forward strand). Ensembl gene ENSG00000196273.
Diseases named in the same sentence as LINC00523 in open-access papers:
LINC00523 is named in the same sentence as 3 diseases in open-access papers, as found by Europe PMC text mining. Sharing a sentence is not in itself a finding about the gene and the disease. The quoted sentences say what the papers report.
gastric cancer (1 paper, 2019). A primary or metastatic malignant neoplasm involving the stomach. "The expression of SNHG4 and LINC00523 was up-regulated in gastric cancer." (PMID 30430424, 2019).
type 2 diabetes mellitus (1 paper, 2024). A type of diabetes mellitus that is characterized by insulin resistance or desensitization and increased blood glucose levels. "Functional effect of the rs79229764 variant on LINC00523 expression is currently unknown, however LINC00523 has been previously shown to be downregulated in patients with type 2 diabetes mellitus (T2DM)." (PMID 39334510, 2024).
cancer (1 paper, 2019). A tumor composed of atypical neoplastic, often pleomorphic cells that invade other tissues. "While the mechanism of SNHG4 and LINC00523 on cancer initiation and progression is remained elusive." (PMID 30430424, 2019).